PAX6 (paired box 6)
Diseases named in the same sentence as PAX6 in open-access papers (continued):
Sharing a sentence is not in itself a finding about the gene and the disease.
glioma (continued). "Bioinformatics analysis using LDA of glioma datasets from the GEO database revealed widespread dysregulation of iron metabolism-related genes, suggesting a possible regulatory relationship between low PAX6 expression and iron metabolism disruption." (PMID 41154694, 2025). "Moreover, the expression level of PAX6 varies significantly among patients with different grades of gliomas (mainly grades 2–4, classified according to WHO CNS5 Tumour Classification (2021))." (PMID 41154694, 2025). "Therefore, it is important to study and elucidate the biological function of PAX6 in glioma to further our understanding of the occurrence and development of glioma." (PMID 41154694, 2025). "Cross-analysis identified 142 common DEGs in both cell lines, suggesting that these 142 differential genes may play an important role in gliomas in PAX6-OE." (PMID 41154694, 2025). "In addition, qPCR and Western blot analysis further confirmed that PAX6 mRNA and protein were significantly lower in glioma cell lines (U251 and U373) compared to normal human fetal glial cells (HMO6)." (PMID 41154694, 2025). "In this study, we established glioma cell lines with stable PAX6 overexpression and integrated bioinformatics, molecular, and animal model approaches to systematically investigate the regulatory relationship between PAX6 and HIF-1α." (PMID 41154694, 2025). "In contrast, in gliomas and prostate cancer, PAX6 functions as a tumor suppressor." (PMID 41154694, 2025). "Then, some relative indicators of ferroptosis regulated by PAX6 in glioma were studied." (PMID 41154694, 2025). "To preliminarily investigate whether PAX6 induces ferroptosis, we transiently transfected glioma cells (U251 and U373) with a PAX6 overexpression plasmid (pcDNA3.1-PAX6)." (PMID 41154694, 2025). "However, how PAX6 plays a tumor-suppressing role in glioma and the specific molecular basis of PAX6’s tumor-suppressive function in gliomas needs to be further elucidated." (PMID 41154694, 2025). "Overexpression of PAX6 can inhibit the proliferative capacity of glioma cells." (PMID 41154694, 2025). "Interestingly, PAX6 expression of glioma cells seems to be inversely correlated with angiogenesis in Pan-NENs." (PMID 33182335, 2020). "There has not been identified PAX6 mutations in gliomas, and the lower expression is probably caused by epigenetic changes as the tumors develop." (PMID 29716531, 2018). "PAX6 suppresses glioblastoma cell growth, anchorage-independent growth and glioma angiogenesis as well as invasiveness of glioblastoma cell, via inhibition of matrix metalloproteinase-2 (MMP2) expression and vascular endothelial growth factor A (VEGFA) expression." (PMID 24454925, 2014). "Taken above studies together, it suggested that BPA exposure might activate Shh to down-regulate Sox2 and Pax6 potentially for glioma and medulloblastoma brain cancers." (PMID 25051057, 2014). "Thus, further research is warranted to explore PAX6 as a potential therapeutic target for glioma." (PMID 41154694, 2025). "Thus, our findings validate that activating PAX6 can impede glioma cell growth both in vitro and in vivo, with one mechanism inducing ferroptosis in glioma cells, suggesting that PAX6 could serve as a promising target for glioma." (PMID 41154694, 2025). "Consequently, the growth rate of PAX6-overexpressing tumors was partially reduced, as evidenced by changes in tumor weights and volumes, demonstrating the inhibitory effect of PAX6 overexpression on glioma growth in vivo." (PMID 41154694, 2025). "Interestingly, PAX6 could maintain astrocytic glioma cells in the G1 phase of the cell cycle, suggesting that PAX6 promotes cell cycle arrest in glioma." (PMID 34459131, 2021).
glioma (continued). "One knows very little about the mechanisms that render PAX6 positive cells more sensitive to increased ROS levels, but our results confirm the finding of Chang and colleagues and show that several sources of ROS have the same effect on glioma cells expressing PAX6." (PMID 29716531, 2018). "Our study aligns with these findings, showing that PAX6 overexpression suppressed the expression of the HIF-1α gene and protein in glioma cells, whereas concurrent overexpression of PAX6 and HIF-1α mitigated the ferroptosis impact generated by PAX6." (PMID 41154694, 2025). "The markers were glioma stem cell markers (CD133 and Msh1), neuronal lineage markers (nestin, sox1, sox2, and pax6), and differentiated markers (GFAP, Tuj1, and Olig123)." (PMID 33575478, 2021). "Furthermore, we explored the potential mechanistic role of PAX6 dysregulation in modulating HIF-1α and ferroptosis in gliomas." (PMID 41154694, 2025). "Consequently, it is imperative to investigate the influence of the regulatory interaction between PAX6 and HIF-1α in glioma formation and development." (PMID 41154694, 2025). "Additionally, further investigation of the regulatory effects of HIF-1α on ferroptosis-related molecules in glioma cells revealed that HIF-1α overexpression decreased LPO levels and increased GSH concentrations, counteracting the ferroptosis-promoting effects of PAX6." (PMID 41154694, 2025). "Transcriptomic and epigenomic analyses have revealed that PAX6/DLX6 promotes the differentiation of WNT5A-mediated glioblastoma stem cells into endothelial-like cells, which serve as an environmental niche supporting the growth of invasive glioma cells throughout the brain parenchyma." (PMID 35682795, 2022). "However, limitations persist, as we have not completely clarified the mechanisms by which PAX6 regulates HIF-1α nor have we fully explored the specific interactions between oxidative stress and iron metabolism in gliomas, which requires further investigation." (PMID 41154694, 2025). "Notably, the correlation between PAX6 and HIF-1α has not been previously reported, and our findings suggest a potential negative regulatory relationship between these two factors in gliomas." (PMID 41154694, 2025).
glioblastoma (22 papers, 2010 to 2025). The most malignant astrocytic tumor (WHO grade IV). "Proliferation and colony formation of glioblastoma cells increased when miR-335 caused an approximately 2-fold downregulation of PAX6, and astrocytes from PAX6 (sey/sey) mutant mice proliferate faster than the corresponding cells in the WT mice." (PMID 29716531, 2018). "MiR-223 overexpression and AN2/PAX6 knockdown caused growth and invasion of glioblastoma cells and increased matrix metalloproteinases, MMP-2, MMP-9, and VEGF-A expression." (PMID 25177699, 2014). "In glioblastoma, low PAX6 expression correlates with unfavorable patient outcomes, and transfecting glioblastoma cells with PAX6 triggers cell death." (PMID 38473380, 2024). "In glioblastoma, a few studies have suggested that a low PAX6 expression level should be considered prognostically pejorative." (PMID 36551712, 2022). "Blocking the miR-223/PAX6 pathway improved sensitivity to chemotherapeutic treatment with temozolomide in glioblastomas, indicating the role of miR-223 in drug resistance." (PMID 35205289, 2022). "miR-223 is another well-recognized oncogenic miRNA, which, in glioblastoma, promotes growth and invasion of tumor cells by targeting the tumor suppressor PAX6, exerting its function by inhibiting the expression of metalloproteases MMP2 and MMP9." (PMID 33287106, 2020). "The U251 N PAX6 knock out cell lines generated can be used as a tool to study the molecular functions and mechanisms of PAX6 as a tumor suppressor with regard to tumor progression and treatment of glioblastoma." (PMID 29716531, 2018). "The aim of the present study was to develop a PAX6 knock out cell line as a tool for molecular studies of the roles PAX6 have in attenuating glioblastoma tumor progression." (PMID 29716531, 2018). "Regulation of PAX6 expression levels by miR-335 indicates that PAX6 restrict cell proliferation in glioblastoma cell lines." (PMID 29716531, 2018). "With our novel tool and new approach to study the role of PAX6 in glioblastoma, we have established that PAX6 influence the cell cycle distribution, and renders U251 cells more sensitive to oxidative stress." (PMID 29716531, 2018). "In our studies, we have as the first created a tool by successfully knocking out PAX6 in the U251 N glioblastoma cell line using the CRISPR-Cas9 technology." (PMID 29716531, 2018). "In anaplastic astrocytic glioma, PAX6 expression is inversely related to tumor grade, resulting in low PAX6 expression in Glioblastoma, the highest-grade astrocytic glioma." (PMID 29716531, 2018). "There are also strong indications that PAX6 is involved in regulating glioblastoma cell cycle by arresting cells in G0/G1-phase, leading to slower proliferation." (PMID 29716531, 2018). "We have demonstrated that complete absence of PAX6 by KO causes increased proliferation, migration and colony forming abilities, confirming that PAX6 acts as a tumor suppressor in glioblastoma cells lines." (PMID 29716531, 2018). "In glioblastoma cell lines, ectopic PAX6 expression downregulates matrix metalloproteinase-2 (MMP2) and suppresses invasiveness." (PMID 29716531, 2018). "PAX6 has been showed to inhibit WNT5A-mediated glioblastoma stem cell (GSC) differentiation into endothelial-like cells, where silencing of PAX6 by activation of the AKT- pathway increased proliferation, vascularization, and invasive growth." (PMID 29716531, 2018). "We found the Nrf2 expression to be regulated by PAX6 in glioblastoma cells, although it cannot be responsible for the increased resistance for oxidative stress observed in our PAX6 KO cells, since it is downregulated by 3.7 fold in this cell line." (PMID 29716531, 2018). "From the development of anaplastic astrocytoma into stage IV glioblastoma the expression level of PAX6 decreases by 3 fold, and GBM tumors have 2–12 fold less PAX6 expression compared to surrounding normal tissue." (PMID 29716531, 2018).
glioblastoma (continued). "The RT-qPCR results differing from theories based on what others have found shows the complexity of the processes involved in increased tumorigenecity in the PAX6 KO cells and in glioblastomas in general." (PMID 29716531, 2018). "Chang and colleagues showed that U251 glioblastoma cells are more sensitive to oxidative stress when overexpressing PAX6." (PMID 29716531, 2018). "We found that CAV1 is 2-fold downregulated in the PAX6 KO cells compared to WT, which fit with observations in other glioblastoma cell lines where lower expression of CAV1 equals increased proliferation." (PMID 29716531, 2018). "MiR-223 targets an aniridia type II protein (AN2/PAX6) or oculorhombin, a transcription factor present during embryonic development, and acts as a tumor suppressor in glioblastoma, as well." (PMID 25177699, 2014). "PAX6 has been described as a tumor suppressor, suppressing invasiveness of glioblastoma cells and MMP2 expression, both of which are hallmarks of EMT." (PMID 24283570, 2013). "PAX6, a transcription factor, has currently been suggested to function as a tumor suppressor in glioblastoma and to act as an early differentitation marker for neuroendocrine cells, which is frequently methylated in human cancers." (PMID 21639921, 2011). "PAX6 dysfunction is also involved in the pathogenesis of glioblastoma." (PMID 35682795, 2022). "Moreover, in Glioblastoma, miR-223 was found to promote temozolomide chemoresistance in glioblastoma multiforme cells by targeting paired box 6 signaling." (PMID 32577098, 2020). "There are reports linking PAX6 to oxidative stress in glioblastoma cells." (PMID 29716531, 2018). "To investigate if PAX6 and its ability to render cells more sensitive to oxidative stress would play a role in treatment of glioblastoma, we treated the PAX6 KO cells and controls with various chemotherapeutic agents; Temozolomide (TMZ), Withaferin A (WA) and Sulforaphane (SFN)." (PMID 29716531, 2018). "The CRISPR-Cas9 technology was used to knockout PAX6 from the U251 N glioblastoma cell-line." (PMID 29716531, 2018). "In glioblastoma, PAX6 has been shown to function as a tumor suppressor." (PMID 25029272, 2014). "In addition to organ development, PAX6 is also expressed in a wide range of cancer cell lines and helps inhibit the growth of glioblastoma and prostate carcinoma cell lines in vitro, implying that the downregulation of PAX6 promotes tumor growth and invasiveness." (PMID 33182335, 2020). "TMZ causes increased PAX6 expression in glioblastoma cell lines U251 and U118, and TMZ is reported to depend on PAX6 expression to decrease proliferation of GBM cells." (PMID 29716531, 2018). "This study identifies key gliogenic genes/signaling pathways having the ability to control oncogenesis in glioblastoma cells including p300, BMP, PAX6 (anti-GBM override), HOPX (tumor suppressive + differentiation), NRSF/REST (astrcytogenic but capable of playing oncogenic role), LIF, and TGF beta." (PMID 35538578, 2022). "Key gliogenic genes having the ability to control oncogenesis in glioblastoma cells: p300, BMP, PAX6, HOPX, NRSF/REST, LIF, and TGF beta.TGF beta: It has a very important gliogenic effect." (PMID 35538578, 2022). "This study identifies key gliogenic genes having the ability to control oncogenesis in glioblastoma cells, including p300, BMP, PAX6, HOPX, NRSF/REST, LIF, and TGF beta." (PMID 35538578, 2022). "miR-7 has shown anti-proliferative effects in many cancers through its target oncogenes such as AKT in hepatocellular carcinoma, EGFR in glioblastoma (GBM), and PAX6 in colorectal cancer." (PMID 34162394, 2021). "Since the level of the PAX6 protein expression changes with the grade of glioblastoma, the observed variation in drug responses can be valuable information when planning treatment and developing new chemotherapies for GBM patients." (PMID 29716531, 2018).
glioblastoma (continued). "Complete absence of PAX6 in our KO cells increased colony formation, and by that we confirmed the role of PAX6 in reducing the glioblastoma cell lines ability to form colonies from a single cell." (PMID 29716531, 2018). "PAX6 knockdown did not influence DKK3 expression in the HeLa (human cervix carcinoma) or U-87 (human glioblastoma) cell lines (results not shown)." (PMID 25029272, 2014). "Expression of Pax6 in glioblastoma multiforme (GMB) is associated with good prognosis, but in published papers on PAX6 and glioblastoma the authors do not distinguish between the two Pax6 isoforms." (PMID 22384097, 2012). "To validate the data from bulk mRNA seq, we selected a set of neural and glial‐specific genes (i.e., PAX6, BRN2/POU3F2, NF‐L/NEFL, and GFAP) showing high expression in the GLICO model in comparison to independently cultured glioblastoma spheroids or standard glioblastoma 2D culture." (PMID 36744875, 2023). "Finally, the rescue construct provided the main isoform PAX6, and not the PAX6(5a) isoform, which is shown to play a part in eye, pancreas, neural development, pancreatic cancer and glioblastoma development." (PMID 29716531, 2018). "However, for the lung cancer cell lines NCI-H661 and NCI-H640, the glioblastoma cell line GaMG and the prostate cancer cell line PC3, PAX6 knockdown by siRNA resulted in an increased Dkk3 expression, indicating that endogenous PAX6 repressed Dkk3 expression in these cancer cell lines." (PMID 25029272, 2014). "It is therefore not known whether Pax6(5a) is expressed in glioblastoma, and in what frequency compared to Pax6." (PMID 22384097, 2012). "For example, PAX6 is prone to hypermethylation in cancer but not in glioblastomas." (PMID 23034185, 2012). "However, the mechanisms behind the tumor suppressor functions of PAX6 in glioblastoma are not fully revealed, and further studies are needed both for the development of new drugs, and for the understanding of the observed resistance to present glioblastoma drug treatments." (PMID 29716531, 2018).